MTOR (mechanistic target of rapamycin kinase)
Diseases named in the same sentence as MTOR in open-access papers (continued):
Sharing a sentence is not in itself a finding about the gene and the disease.
cancer (continued). "Deregulation of multiple elements of the mTOR signaling pathway, especially, the overexpression of 4EBP1 and S6K1 had been reported in many kinds of cancer, and the overexpression of these major components of the mTOR signaling pathway had a remarkably effects on tumour progression." (PMID 28406985, 2017). "In a wide variety of cancers, RPS6KB1 is regulated by Akt/mTOR signaling pathway." (PMID 28792981, 2017). "It has been well established in experimental studies that metformin exerts the anti-cancer activity through activation of AMPK and subsequent inhibition of the mTOR pathway, which is a downstream effector of growth factor signaling and is frequently activated in cancer cells." (PMID 27903961, 2017). "The functional enrichment analysis suggested that the target genes of three miRNAs may be involved in various pathways related to cancer, including MAPK, AMPK, focal adhesion, cGMP-PKG, wnt, and mTOR signaling pathway." (PMID 28717180, 2017). "In another similar study, Balb/c mice injected with A549 cells were treated with 400 mg/kg/day metformin and 30 mg/kg/day sorafenib for 40 days and were shown to have decreased cancer cell proliferation, decreased tumor size, increased AMPK phosphorylation and inhibition of mTOR signaling." (PMID 28481268, 2017). "Metformin suppresses cancer growth via AMPK phosphorylation, thereby inhibiting mTOR activity." (PMID 29163155, 2017). "In recent years, increasing evidence strongly suggests that autophagy is fundamentally elevated in cancer tissue regardless of Akt/mTOR signal activation, indicating that autophagy has been induced mostly as a protective mechanism in cancer cells." (PMID 29100416, 2017). "MTOR showed a disperse distribution throughout the cytoplasm when cancer cells were incubated in the absence of amino acids." (PMID 28112156, 2017). "Unlike BCL-2 inhibition, which failed to sensitize cancer cells to PI3K/mTOR treatment, BCL-XL inhibition increased cell killing by GNE-493 in most of the PDX models." (PMID 28848242, 2017). "Correlation of such data with clinical outcome may allow development of strategies for optimized (combinatorial) cancer therapies, to simultaneously target PLK1 and MTOR in tumors where MTORC1 is activated by PLK1 inhibition." (PMID 28102733, 2017). "It has been proposed that metformin exerts its anti-cancer properties through direct effects on cancer cells, particularly through inhibition of the AMPK/mTOR pathway, and indirect effects by decreasing glucose, insulin, insulin-like growth factor 1 (IGF-1) levels, and other inflammatory factors." (PMID 29113364, 2017). "Twelve patients in the mTOR inhibitor group and 24 in the non-conversion group died of cancer progression." (PMID 28160552, 2017). "In addition, CPT exerts inhibition on mTOR with simultaneous activation of AKT in Rh30 and DU145 cancer cells." (PMID 28272775, 2017). "These three mouse cancer cell lines showed increased phospho-AKT expression when compared with the OVdT4088 line, and expectedly, showed stronger expression of the downstream phospho-mTOR target." (PMID 27602775, 2016). "Thus, we observed decreased glycolysis in the tumor cells treated with API-2 or everolimus, in line with recent reports in other human cancer cells, as well as with the connection between AKT/mTOR/p70S6K signaling in cancer and glycolysis." (PMID 26771843, 2016). "However, even if in GBM, the presence of autophagy inducers such as RAD001 (mTOR inhibitor) allowed TMZ to induce an autophagic death signaling, only few cancers responded to such treatment." (PMID 27787518, 2016). "Our findings suggest that combinational therapies that target mTOR/HIF-1α/SK1 may overcome docetaxel resistance and have a clinical benefit in human cancers." (PMID 27821815, 2016).
cancer (continued). "Through inhibition of prenylation of Ras and Rho proteins, statins may suppress extensive downstream signalling pathways of these proteins, such as the PI3K/Akt/mTOR and MAPK/ERK pathways, which are commonly abrogated in many types of cancer." (PMID 26565813, 2016). "Since mTOR inhibition increases AKT activity by disrupting feedback inhibition, vertical targeting of the PI3K-AKT-mTOR pathway has proven to be a promising approach in several cancer types, with clinical trials ongoing." (PMID 27374095, 2016). "It has been proposed that the anti-cancer properties of metformin result from both direct effects on cancer cells, particularly through inhibition of the AMPK/mTOR pathway, and indirect effects on the host, by virtue of its blood glucose-lowering properties and anti-inflammatory effects." (PMID 27681864, 2016). "Though rapalog therapies have shown clinical efficacy in a subset of cancers, this mode of drug action does not fully exploit the anti-tumor potential of mTOR pathway targeting." (PMID 29083380, 2016). "In line with this mTOR dependency, we found that resveratrol suppresses the viability of MCF7 cells but not of SW620 cells, which are mTOR inhibitor sensitive and insensitive cancer cells, respectively." (PMID 26902888, 2016). "This cancer driver overreliance may in turn render HNSCC particularly sensitive to PI3K and mTOR inhibitors." (PMID 26882569, 2016). "Currently, the first-generation mTOR inhibitors (rapalogs) are used in clinical trials for treating HCC but do not show the expected efficacy; combining mTOR inhibition with sorafenib enhanced the antitumoral effect in cancer models, including HCC56." (PMID 26879559, 2016). "mTOR is a serine/threonine protein kinase downstream PI3K/Akt pathway, which controls cell growth, proliferation, survival, metabolism and angiogenesis and is involved in cancer development." (PMID 26895472, 2016). "Phospho-mTOR/mTOR was also detected in the KPNA2-immunoprecipitated complex, which indicated that the induction of KPNA2 protein decay is a possible mechanism of rapamycin functioning in anti-cancer processing." (PMID 27009856, 2016). "Many studies have shown that mTOR signaling activates EMT, cancer invasion, and metastasis." (PMID 26771232, 2016). "Since inhibition of Akt or mTOR alone does not completely inhibit this pathway, dual PI3-K/mTOR or mTORC1/mTORC2 inhibitors are considered to be a viable alternative to aggressive cancer therapy." (PMID 27285995, 2016). "We designed a phase I study to determine the safety, maximum tolerated dose (MTD), recommended phase II dose (RP2D), and dose-limiting toxicities (DLTs) of combined mTOR inhibitor sirolimus (1 mg-5 mg PO daily) and HDAC inhibitor vorinostat (100 mg-400 mg PO daily) in patients with advanced cancer." (PMID 27589687, 2016). "As observed for the protein, the level of 4E-BP3 mRNA, but not 4E-BP1 or 2, was increased after treatment with mTOR inhibitors in the three cancer cell lines." (PMID 27319316, 2016). "To gain new insight into mTOR inactivation in cancer models, we characterized one such novel compound and designated it as mTOR inhibitor-31 (MTI-31)." (PMID 27563814, 2016). "Thus, the PIM pathway seems to be required for optimal engagement of mTOR targets in GBM, in line with observations from other cancers." (PMID 27120806, 2016). "AZD2014 is a newer, second generation mTOR inhibitor that blocks activation of both mTORC1 (phosphorylation of 70S6K1 and 4EBP1) and mTORC2-mediated AKT Ser473 phosphorylation, and activates apoptosis in cancer cells." (PMID 27031247, 2016). "Thus, mTOR could be an attractive target for anticancer therapy, indeed, many mTOR inhibitors have been developed and are undergoing clinical trials to fight against various types of cancers, like sirolimus (CCI-779), everolimus (RADD001) and ridaforolimus (AP23573)." (PMID 26893358, 2016). "Overexpression of downstream mTOR effectors 4E-BP1 and S6K lead to poor cancer prognosis." (PMID 27888804, 2016).
cancer (continued). "Besides these critical molecules, additional metabolic-related pathways are also crucial for cancer glucose metabolism, especially the PI3K/AKT/mTOR pathway and the AMPK pathway, in particular when tumor cells are exposed to growth factors." (PMID 26934324, 2016). "Our results demonstrated a lack of consistency in the effect of PI3K/Akt/mTOR pathway inhibitors on PCho content of cancer cells, suggesting that this metabolite is not a robust response marker." (PMID 27811956, 2016). "Dual inhibition of mTOR and PI3K has been shown to be a promising approach in cell lines from other cancer types and may be particularly efficacious in bladder where molecular lesions are found in multiple genes in the PI3K pathway, often concurrently." (PMID 27465249, 2016). "RPTOR, mTOR, and MLST8 constitute the core subunits of the mammalian TORC1 (mTORC1) complex which play a major role in the control of cell growth and metabolism and is often deregulated in cancer." (PMID 27799065, 2016). "The genes of mammalian target of rapamycin (mTOR), RICTOR, and RAPTOR survival pathways, which are often overexpressed in majority of the cancers, were significantly downregulated within few hours of the treatment of SKOV3 cells with C1q and globular head modules." (PMID 28066412, 2016). "Although mTOR inhibitors have significantly improved survival of different cancer patients, resistance and lack of predictive factors of response remain unsolved issues." (PMID 27223077, 2016). "Other studies even found that mTOR signaling was activated rather than suppressed during cancer cachexia." (PMID 26856534, 2016). "For example, a mix of metformin, an anti-diabetic drug, and rapamycin, an inhibitor of mTOR, is toxic for cancer cells but cytoprotective for non-cancerous cell types." (PMID 27992857, 2016). "We thus suggest that DCP might protect cancer cells from the Sorafenib-induced apoptosis through activation of the Raf/MEK/ERK and PI3K/Akt/mTOR signaling pathways." (PMID 27167344, 2016). "As is already known, in TGFβ-mediated non-Smad signal transductions, TGFβ induces the Akt/mTOR pathway to promote cancer cell proliferation and invasion." (PMID 27830743, 2016). "Moreover, mTOR/p-mTOR expression could independently predict the worse overall survival (HR: 2.04; 95 % CI: 1.58–2.62; P < 0.001), disease-free survival (HR: 2.39; 95 % CI: 1.64–3.49; P < 0.001) and cancer-specific survival (HR: 1.62; 95 % CI: 1.18–2.23; P = 0.003) of patients with ESCC." (PMID 27835987, 2016). "Nevertheless, a recent study showed that NVP-BEZ235, a PI3K and mTOR dual inhibitor, induced the activation of the MAPK as indicated by enhanced ERK phosphorylation, which likely limit the clinical utilization of it in cancer treatment." (PMID 26940018, 2016). "Moreover they demonstrated that miR-451 activated the PI3K/Akt/mTOR pathway in SP cells through its target tuberous sclerosis 1 (TSC1), this pathway is a well-known oncogenic pathway in cancers including MM." (PMID 27494872, 2016). "The findings from this group and others strongly support the concept that mTOR regulates cell adhesion, which is independent of cancer cell lines or stimuli." (PMID 25762619, 2015). "Since the screen from the Cancer Cell Line Encyclopedia contained few drugs, and these were not highly specific to the AKT/PI3K/mTOR signaling axis, we decided to use the screen generated by the Genomics Drug Sensitivity in Cancer (GDSC) project." (PMID 25886003, 2015). "Moreover, cancer remains a poor prognosis, mainly attributed to the excessive activation of the PI3K-AKT/mTOR signaling pathway." (PMID 25854175, 2015). "Honokiol targets multiple signaling pathways such as nuclear factor κB (NF-κB), signal transducers and activator of transcription 3 (STAT3), mammalian target of rapamycin (mTOR) and epidermal growth factor receptor (EGFR), which have great relevance during cancer initiation and progression." (PMID 25846316, 2015).
cancer (continued). "In addition to inhibiting mTOR and the downstream effectors of the mTOR pathway (4E-BP1 and S6K), Torin2 inhibited the phosphorylation of AKT, an important signaling (PI3K/AKT/mTOR)-pathway in ATC and a variety of cancers." (PMID 25945839, 2015). "mTOR inhibition is in this case not just the way mediating activation of autophagy but an indicator that cancer cell is trying to overcome nutrient deprivation by restricting nascent protein synthesis." (PMID 25821829, 2015). "Despite the cross-talk between EMT programming and the mTOR pathway, the relationship between rapamycin sensitivity in immortalized cancer cells lines and markers of EMT has not been previously investigated." (PMID 25944619, 2015). "Studies have shown that mTOR signalling can activate Gli1 expression through canonical and non-canonical pathway in human cancer cells 14,19." (PMID 26218750, 2015). "In addition to its effects on mTOR, curcumin modulates additional cellular pathways, including JAK-STAT, NF-κB, and MAPK, that impact telomerase regulation and cancer cell growth." (PMID 25869441, 2015). "We propose that activation of the phosphatase activity towards ULK1 represents a mechanism that allows cancer cells to activate a strong autophagy flux without turning off mTOR activity, thus achieving optimal growth and survival capability." (PMID 26310906, 2015). "This signaling cascade is highly important in several types of cancers due to the fact that AKT and mTOR can regulate numerous tumorigenic events including cell proliferation, cell cycle progression, apoptotic resistance, autophagy, nutrient-dependent growth, and protein translation initiation." (PMID 25999352, 2015). "We did not detect any expression change of TSC2, ACC, and mTOR phosphorylation in these cancer cells after induction of PKR." (PMID 25798539, 2015). "Indeed, Redd1 can inhibit mTOR activity through activation of TSC2, suggesting a possible role for Redd1 in metformin anti-cancer effects in human GB cells." (PMID 25867026, 2015). "Moreover, in many cancers, a defect in the PI3K/AKT/mTOR and MAPK/ERK pathways plays a crucial role in the development and progression of the disease." (PMID 26402860, 2015). "Because the EMT process can be regulated by a diverse array of cytokines and growth factors, we analyzed the activation status of several kinases and their effectors involved in cancer cell proliferation and survival, including EGFR, IGF-1R, Src, FAK, Akt, Erk1/2, mTOR, MEK1/2, and p70S6K." (PMID 26416450, 2015). "Considering the similarities between the inhibition of survivin and mTOR in our HNSCC model and the extensively reported effects of mTOR inhibitors on cancer stem cells, future studies should explore the combined therapeutic effect of YM155 on cancer stem cells." (PMID 26018732, 2015). "Pharmacological mTOR inhibitors have emerged as lead candidates for so-called calorie restriction (CR) mimetics, agents that mimic the anti-cancer or anti-aging effects of CR without the restriction of dietary energy intake." (PMID 26029167, 2015). "The pathway enrichment analysis results showed that most of the genes common to meta-miRNA targets and meta-mRNAs took part in important pathways such as cancer specific pathways, the cell cycle, TGF-beta signaling pathway, apoptosis, MAPK, mTOR and VEGF signaling pathways (p≤ 0.0205)." (PMID 25978727, 2015). "There is evidence that mTOR inhibition impairs the proliferation and survival of c-Myc-overexpressing cancer cells, but this inhibition does not directly involve an effect on expression of the c-Myc protein." (PMID 25402633, 2015). "The mammalian target of rapamycin (mTOR) has been identified to be a downstream target of the PI3K/Akt pathway, and it has emerged as a critical effector in cell signaling pathways commonly deregulated in human cancers." (PMID 26497956, 2015).
cancer (continued). "Collectively, it suggests that induction of cell cycle arrest, promotion of apoptosis and autophagy, and suppression of EMT involving mitochondrial, death receptor, PI3K/Akt/mTOR, p38 MAPK, and AMPK signaling pathways contribute to the cancer cell killing effect of ALS on CRC cells." (PMID 26729093, 2015). "Studies have shown that activation of mTOR and its downstream effectors in spinal cord (but not in DRG) are implicated in cancer pain." (PMID 26024835, 2015). "Our results suggest that XBP1 exerts its effect on OS probably by influencing PI3K/mTOR signaling, which could be a novel mechanism by which XBP1 promotes cancer progression." (PMID 26633383, 2015). "In cancer cells, metformin interferes with the PI3K/AKT/mTOR pathway, and indirectly inhibits mTOR." (PMID 25504439, 2015). "This strategy has allowed accurate prospective identification of cancer cells sensitive to the pan-Class I PI3K agent pictilisib (false-discovery rate or FDR < 10−10) and the dual class I PI3K/mTOR drug GDC-0980 (FDR < 0.0019), as well as other targeted agents in a large panel of cancer cell lines." (PMID 26117819, 2015). "Our work discloses that celastrol, in a NF-κB inhibition/mTOR activation-related way, induces miR-223 in MCF-7 and PC3, and that down-regulating miR-223 could further reduce living cancer cells in samples treated with celastrol." (PMID 26552919, 2015). "Conversely, PI3K/Akt/mTOR pathway intermediates showed an equal distribution between non-muscle invasive bladder cancer (NMIBC) and MIBC and did not associate with cancer-specif survival (CSS) in any of these groups." (PMID 26569621, 2015). "Similar effects of miR-497 on targeting mTOR and p70S6K1 have also been observed in multiple human cancer cells (data not shown)." (PMID 26238185, 2015). "Some research indicates that mTOR expression can be increased in most human cancers and growing evidences demonstrate that mTOR plays a role not only in the formation of tumors, but also in the cancer progression." (PMID 26357655, 2015). "Molecular therapies targeting mTOR, have being actively investigated and many of these have now progressed to clinical trials in many different types of cancer." (PMID 26397134, 2015). "In addition to single agent activity, these inhibitors also act synergistically with other cancer therapeutic agents such as HDAC inhibitors, mTOR inhibitors, and PI3K inhibitors in inducing apoptosis and inhibiting the growth of cancer cells and tumors." (PMID 26415225, 2015). "Similar to studies that have examined the role of mTOR signaling in CSCs, the regulation of CSC biomarker proteins and the process of tumorigenesis in many cancers, our results prove that the mTOR signaling pathway plays a significant role in influencing CSC behavior in human primary NPC." (PMID 26202311, 2015). "mTOR’s role in cancer treatment is not simply limited to its effects on neoplastic cell survival and proliferation." (PMID 26024835, 2015). "In this study, our results demonstrated that HBx stimulates the neoplastic transformation of normal cells and tumor induction by AFP triggering of the PI3K/mTOR signal to promote expression of Src, Ras, and CXCR4, which are known to promote the progression, invasion, and metastasis of cancer cells." (PMID 25682869, 2015). "Inhibition of mTOR signaling may prevent CSC self-renewal and circumvent CSC-mediated resistance to cancer therapeutics." (PMID 25749036, 2015). "Collectively, these data suggest that RY-2f exerts its anti-cancer function, at least partially, through disruption of the PI3K/AKT/mTOR signal pathway, which may consequently result in cellular apoptosis." (PMID 26325371, 2015). "Flagellin governs the proliferation of T cells and cancer cells by upregulating cytokines and chemokines, including TNF-α and IL-6, and the role of mTOR signaling in flagellin-induced inflammatory responses is unknown." (PMID 25942007, 2015).